H19 (H19 imprinted maternally expressed transcript)
Diseases named in the same sentence as H19 in open-access papers (continued):
Sharing a sentence is not in itself a finding about the gene and the disease.
bladder cancer (continued). "Notably, single nucleotide polymorphisms (SNPs) of H19 are used to predict the risk of cancer, such as rs2839698 and rs2107425 genotypes are found to be related to decreased risk of bladder cancer." (PMID 33330574, 2020). "These polymorphic variants may play a role in metastasis and are possibly linked to H19 gene re-expression for bladder cancer progression and recurrence." (PMID 31013794, 2019). "Thus far, most studies have addressed the identification of H19 gene SNPs in bladder cancer 26, hepatocellular cancer 27, and lung cancer 28, whereas few studies focused on the role of H19 gene SNPs in neuroblastoma risk." (PMID 31772668, 2019). "Studies have explored the possible role of H19 single-nucleotide polymorphisms (SNPs) in various cancers, such as breast cancer, oral squamous cell carcinoma, lung cancer, hepatocellular cancer, and bladder cancer." (PMID 31013794, 2019). "H19 SNP rs2839698 mutation has been reported to reduce the risk of bladder cancer." (PMID 31772651, 2019). "A previous study showed that H19 was positively associated with ID2 expression in bladder cancer." (PMID 29643943, 2018). "Additionally, the effect of H19 rs2107425 also was investigated on the risk of bladder cancer and ovarian cancer." (PMID 28159929, 2017). "H19 regulates bladder cancer metastasis through its association with EZH2." (PMID 26623562, 2016). "In addition, a population‐based case‐control study genotyped 177 patients with bladder cancer and 122 healthy controls for H19 rs2839698, finding that the rs2839698 TC genotype significantly reduced the risk of bladder cancer compared to the rs2839698 TT genotype." (PMID 33236528, 2021). "Furthermore, the rs217727 (G>A) H19 polymorphism has been associated with increased risk of osteosarcoma, whereas another study found that the polymorphism was also associated with increased risk of bladder cancer." (PMID 33236528, 2021). "Moreover, Chinese patients with invasive bladder cancer carrying the H19 rs3024270 CC genotype may exhibit a decreased risk and good prognosis for bladder cancer." (PMID 31013794, 2019). "Furthermore, a recent study indicated that upregulated H19 could accelerate bladder cancer metastasis by associating EZH2 and inhibiting expression of -E-cadherin, which was the EMT-induced marker." (PMID 27825121, 2016). "For instance, previous studies have shown that H19 can serve as a biomarker not only for ischemic stroke, but also for gastric, lung, and bladder cancers and other diseases." (PMID 39766887, 2024). "It has already been demonstrated that the therapeutic use of the H19-regulated double-stranded DNA plasmid BC-819 has been evaluated and found to be effective in patients who have bladder cancer." (PMID 39512820, 2024). "A study linking H19 to cancer reported that H19 was elevated in bladder cancer and considered it a predictor of early cancer recurrence." (PMID 39184399, 2024). "Studies have reported that the expression of exosome-lncRNA H19 in serum of bladder cancer patients is upregulated, and exosome-lncRNA PTENP1 in plasma is downregulated, both of which can serve as good tumour markers for bladder cancer diagnosis." (PMID 37592177, 2023). "We revealed the effect of TAMs-exo-contained lncRNA H19 on regulating autophagy of bladder cancer cells, which indicated that targeting TAMs-H19 is a promising therapeutic strategy for the treatment of BC." (PMID 35607322, 2022). "H19 has been shown to associate with EZH2 and increase bladder cancer metastasis, or as an miRNA sponge to enhance the expression of oncogenes." (PMID 36578923, 2022). "Then in vivo and in vitro experiments have further confirmed that up-regulation of lncRNA H19 can accelerate the metastasis of bladder cancer cells." (PMID 36406273, 2022).
bladder cancer (continued). "This study suggests that H19 plays a role in autophagy induction in bladder cancer cells and targeting TAMs-Exosomes-H19 is an encouraging therapeutic approach for the management of bladder cancer." (PMID 36685879, 2022). "Authors have shown that H19 overexpression increased the migratory properties of bladder cancer cells by interaction with EZH2 which leads to activation of Wnt/β-catenin signaling and therefore led to EMT induction." (PMID 36685879, 2022). "What’s more, in bladder cancer, H19 has been found to interact with polycomb repressive complex 2 (PRC2) by associating with enhancer of zeste homolog 2 (EZH2), which leads to the silencing of the E-cadherin gene." (PMID 36246634, 2022). "H19 has been shown to enhance bladder cancer cell proliferation via the upregulation of an inhibitor of DNA binding 2 (ID2)." (PMID 36685879, 2022). "A phase I/II clinical trial showed that BC-819, a plasmid with an lncRNA H19 promoter, showed 22% complete response rates and 44% partial response rates in treating bladder cancer." (PMID 35898869, 2022). "It is worth noting that, in addition to bladder cancer, the researchers found that lncRNA H19 also plays a regulatory function in prostate cancer." (PMID 36406273, 2022). "As an oncogenic lncRNA, exosomal H19 can be detected in bladder cancer patients’ serum and plasma, which has been considered as a highly potential cancer biomarker in bladder cancer." (PMID 36566321, 2022). "H19 is significantly upregulated in most bladder cancer tissues and invasive bladder cancer cell lines." (PMID 34977037, 2021). "It was also reported that H19 promotes epithelial-mesenchymal transition and metastasis of bladder cancer via H19/miR-29b/DNMT3B signaling pathway in cytoplasm." (PMID 34422802, 2021). "In bladder cancer, several lncRNA/miRNA axes have acted as regulators of cancer metastasis, including lncRNA H19/miR-29b, lncRNA XIST/miR-124 and lncRNA UCA1/miR-196a." (PMID 33902589, 2021). "Previous research has found that the level of lncRNA H19 is up-regulated in bladder cancer and then promotes the metastasis of bladder cancer by inducing epithelial–mesenchymal transformation, thus promoting the occurrence and development of bladder cancer." (PMID 34026626, 2021). "Clinically, there are many types of lncRNA associated with bladder cancer, including HOTAIR, MALAT1, H19, etc., all of which play an important role in the occurrence and development of bladder cancer." (PMID 33898446, 2021). "H19 directly binds to EZH2 in bladder cancer, resulting in a reduction in EMT epithelial marker E‐cadherin." (PMID 34977870, 2021). "BC-819 has completed phase 1/2a trials in pancreatic, ovarian and bladder cancers, with current clinical development focused on bladder cancer, where H19 is often suppressed in normal cells but upregulated in tumor cells." (PMID 34316694, 2021). "LncRNA H19 promotes cell proliferation in several disorders, such as pancreatic cancer, hepatocellular carcinoma and bladder cancer." (PMID 34992498, 2021). "H19 has also been shown to act as an miRNA sponge in colorectal, gastric, and bladder cancers, further regulating tumor progression." (PMID 34598322, 2021). "Accumulating evidence have suggested that the levels of H19 are increased in a numerous type of malignancies, such as esophageal, colon, hepatocellular and bladder cancer." (PMID 34796112, 2021). "lncRNA H19 has been reported to accelerate bladder cancer metastasis by recruiting EZH2 and repressing the expression of E-cadherin." (PMID 34401209, 2021). "Previous studies demonstrated that H19 was over-expressed in some types of tumors, such as hepatocellular carcinoma, lung, esophageal, and bladder cancer." (PMID 33800276, 2021). "Kaplan-Meier survival curve showed that the higher the level of serum exosome-derived H19, the lower the survival rate in bladder cancer patients, suggesting that the level of lncRNA H19 in exosomes is of value in predicting the prognosis of bladder cancer." (PMID 34370713, 2021).
bladder cancer (continued). "LncRNA H19, which is located in 11p15.5, is upregulated in various human solid tumors, including bladder cancer, non–small cell lung cancer, breast cancer, and gastric cancer." (PMID 32878251, 2020). "More importantly, it has been shown for bladder cancer diagnosis and prognosis that the concentration of circulating H19 was significantly higher in serum exosomes than in exosomes-depleted supernatants in serum or tissue samples." (PMID 33291403, 2020). "Another work, on bladder cancer (BC), showed a positive correlation among serum exosomal H19 with total H19 level in paired cancer tissues." (PMID 31003545, 2019). "For example, as a part of the complex, lncRNA H19 associated with EZH2 enhancer and inhibited E-cad expression, which resulted in the activation of the Wnt/β-catenin pathway enhancing bladder cancer metastasis." (PMID 31143372, 2019). "H19 is one of the most crucial long noncoding RNAs (lncRNAs) and is involved in various types of bladder cancer." (PMID 31013794, 2019). "In another study, lncRNA H19 levels were remarkably increased in bladder cancer tissues, and up-regulated H19 promoted bladder cancer cells migration by down-regulation of E-cad." (PMID 30217944, 2018). "The safety, tolerability, and efficacy of DTA-H19 have been verified in a phase 1/2a clinical trial for the treatment of H19-overexpressing bladder cancer." (PMID 30374364, 2018). "To date, many aberrantly expressed lncRNAs have been identified in bladder cancer, including upregulated lncRNAs, H19, MALAT1, SNHG16, TUG1, UCA1, TINCR and Linc-UBC1; and downregulated lncRNAs, BANCR and MEG3." (PMID 29719633, 2018). "In bladder cancer, H19 was shown to direct EZH2 to the promoter region of Nkd1, thus inducing the trimethylation of H3K27 and the consequent repression of transcriptional activity." (PMID 29643989, 2018). "Further studies demonstrated that upregulated H19 promoted proliferation and metastasis of bladder cancer cells via upregulation of inhibitor of DNA binding/differentiation 2 (ID2) and downregulation of E-cadherin." (PMID 29719633, 2018). "In bladder cancer, H19 has been proven to interact with PRC2 through EZH2, one of the core components of PRC2 complex by RNA immunoprecipitation assay." (PMID 28230721, 2017). "The H19 RNA inhibits insulin-like growth factor 2 (IGF2) transcription and translation, whereas the H19 SNP promotes mitotic IGF2 expression, thereby decreaseing the risk of bladder cancer." (PMID 29299175, 2017). "From a therapeutic perspective, a plasmid-based strategy (DTA-H19/BC-819) to target H19 is presently in a phase 2b clinical trial for bladder cancer and in phase 1/2a for ovarian and peritoneal cancer." (PMID 29099749, 2017). "The therapeutic usage of H19-regulated double-stranded DNA plasmid BC-819 has already been successfully tested in patients with bladder cancer." (PMID 28241429, 2017). "In an older report, H19 mRNA expression in bladder cancer was studied by in situ hybridization on paraffin sections." (PMID 28430799, 2017). "For example, H19 is aberrantly expressed in many types of cancer such as liver and bladder cancers and pancreatic ductal carcinoma, while HOTAIR has been implicated in various aspects of cancer development." (PMID 27604105, 2017). "Despite these two mechanisms, there is also evidence of H19 activating Wnt signaling, albeit in a different context and cell type: bladder cancer." (PMID 28933364, 2017). "Currently, a phase I/IIa clinical trial of H19-based constructs (BC-H19/DTA-H19) in bladder cancer has already indicated a response rate of 66%." (PMID 28230721, 2017). "In fact, H19 is involved with various diseases and can be used as a potential prognostic biomarker for the early recurrence of bladder cancer." (PMID 28947982, 2017).
bladder cancer (continued). "So, these data suggest that H19 promotes cell proliferation and miR-675 expression in bladder cancer." (PMID 26198047, 2016). "Emerging evidence showed that long noncoding RNA 19 (H19) possesses oncogenic properties and is the key regulator in carcinogenesis and metastasis of bladder cancer." (PMID 26198047, 2016). "Currently, emerging evidence has confirmed that the human long noncoding RNA H19 is upregulated in many cancers and promotes cancer progression, including bladder cancer." (PMID 26198047, 2016). "In the context of metastasis, the expression of H19 lncRNA is markedly increased in biopsies taken from primary bladder cancer that subsequently metastasized." (PMID 26623562, 2016). "Long noncoding RNA 19 (H19) has been shown to promote bladder cancer cell proliferation and metastasis." (PMID 26198047, 2016). "While several studies reported that H19 functioned as an oncogenic lncRNA promoting tumor metastasis in GC, ovarian cancer, endometrial cancer, and bladder cancer, other studies found that it inhibits tumor metastasis via miR-675." (PMID 27686732, 2016). "We provided further support for these findings by showing that xenografts of tumors derived from H19 over-expressing bladder cancer cells were more vascularized relative to the control." (PMID 26623562, 2016). "Disease-free survival from the first biopsy to the first episode of recurrence was significantly shorter in bladder carcinoma patients with tumors having more H19-positive cells." (PMID 27193186, 2016). "Human bladder carcinoma derived from adult bladder mucosa cells had also lost their ability to express H19 gene." (PMID 27501229, 2016). "Ectopic expression of H19 significantly increased bladder cancer cell proliferation and miR-675 expression in vitro." (PMID 26198047, 2016). "As H19 has been shown to promote proliferation and metastasis of bladder cancer, then we treated 253J cells with miR-675 mimic or inhibitor to verify the role of miR-675 in regulating proliferation of 253J cells and RT4 cells." (PMID 26198047, 2016). "For the bladder cancer, H19 has been considered as a potential prognostic biomarker for the early recurrence." (PMID 27517318, 2016). "H19 positively regulated miR-675 expression in bladder cancer cells, and upregulation of miR-675 significantly promoted cell proliferation of bladder cancer cells in vitro." (PMID 26198047, 2016). "miR-675 was positively regulated by H19, and overexpression of miR-675 increases cell proliferation of human bladder cancer cells." (PMID 26198047, 2016). "It was reported that YAP1 and H19 expression levels were elevated in bladder cancer cells, and H19 expression was found to be significantly associated with YAP1 expression." (PMID 27835600, 2016). "H19 level is elevated in bladder cancer tissues, and upregulated expression of H19 promoted cell motility and metastasis of bladder cancer cells in vivo and in vitro." (PMID 27686732, 2016). "In bladder cancer cells, H19 was found both in vitro and in vivo to promote EMT, down-regulation of E-cadherin and cell migration." (PMID 26536864, 2015). "H19 levels are remarkably increased in bladder cancer tissues, and upregulated H19 enhances bladder cancer metastasis by associating with EZH2 and inhibiting E-cad expression." (PMID 26376677, 2015). "At the same time, as evident from our differential transcriptome analysis studies conducted both in liver and bladder cancer cell lines, H19 enhances tumor survival under harsh conditions." (PMID 26536864, 2015). "Contrary to this, detailed studies of human bladder carcinoma samples indicate that H19 levels decrease with increasing tumor grade." (PMID 25101115, 2014). "Recent studies showed that H19 is overexpressed in several malignancies such as breast cancer, bladder cancer and cervical carcinomas." (PMID 24810858, 2014).
bladder cancer (continued). "Supporting a driving role for H19 in metastasis, both silencing and over-expression of H19 was shown to modulate metastatic behavior in bladder cancer." (PMID 24346158, 2014). "Further characterization of the role of H19 in bladder cancer showed that H19 is commonly overexpressed in primary human tumor samples that subsequently metastasize." (PMID 25101115, 2014). "In bladder cancer, H19 directly binds EZH2 and recruits PRC2 to the E-cadherin promoter, thereby suppressing E-cadherin expression and promoting epithelial-to-mesenchymal transition (EMT)." (PMID 24346158, 2014). "H19 expression is significantly correlated with tumor grade and is a marker of early recurrence in bladder cancer." (PMID 24810858, 2014). "H19 expression levels were remarkably increased in bladder cancer tissue as compared with adjacent normal control tissue." (PMID 24006935, 2013). "Up-regulated H19 not only promotes bladder cancer cell proliferation, but it also promotes cell migration in vitro and in vivo." (PMID 24006935, 2013). "A lncRNA H19 with oncogenic properties is upregulated in a wide range of tumors including bladder cancer and it is an interesting target of alternative cancer treatment." (PMID 24006935, 2013). "Nevertheless, H19 is re-expressed in a number of tumors, including bladder carcinoma, demonstrating that it is an onco-fetal RNA." (PMID 24006935, 2013). "Ectopic expression of H19 promotes bladder cancer cell proliferation in vitro and enhances bladder cancer cell migration, both in vitro and in vivo." (PMID 24006935, 2013). "We have shown that IGF2 or H19 are significantly expressed in 50-84% of human bladder carcinomas, respectively." (PMID 21162716, 2010). "The human IGF2-P4 and H19 promoters are highly active in a variety of human cancers (including bladder cancer), while existing at a nearly undetectable level in the surrounding normal tissue." (PMID 21162716, 2010). "To evaluate the possible use of IGF2-P4 and H19 regulatory sequences for targeted therapy of bladder cancer, we determined the expression of IGF2-P4 and H19 transcripts by RT-PCR, qRT-PCR and ISH." (PMID 21162716, 2010). "We have shown that N-Butyl-N-(4-hydroxybutyl) nitrosamine (BBN) (a known carcinogen of the bladder) added to the drinking water also induces the expression of H19 gene in a rat model of bladder cancer in early stages." (PMID 17786216, 2007). "We previously identified downstream targets modulated by H19 over-expression in the T24P bladder carcinoma cell line." (PMID 17786216, 2007). "Moreover, ICR1 hypomethylation is also considered to be characteristic of H19 LOI and regularly results in the upregulation of H19 mRNA expression in human bladder cancer." (PMID 38812777, 2024). "In bladder cancer, long non-coding RNA H19 from the exosomes of M2 tumor-associated macrophages interfers K48-linked polyubiquitination of ULK1 mediated by NEDD4L, stabilizing ULK1 expression and promoting bladder cancer cell autophagy." (PMID 38027016, 2023). "Exosomal H19 expression has been proven as a marker of breast and bladder cancers." (PMID 37189829, 2023). "In bladder cancer, M2-like macrophage exosome-derived H19 could enhance ULK1 stabilization through alleviating the K48-linked polyubiquitination of ULK1, sequentially facilitating the autophagy of bladder cancer cell." (PMID 37637063, 2023). "Further investigation revealed that H19 directly bound to miR-29b and upregulated the expression of DNA methyltransferase 3 B (DNMT3B), a target of miR-29b, which is associated with the initiation and progression of bladder cancer." (PMID 36605618, 2023). "In addition, previous studies have indicated that lncRNA H19 is abnormally expressed in multiple tumors like ovarian cancer, bladder cancer, and lung cancer as a proto-oncogene." (PMID 37253635, 2023).